SST (somatostatin)
Diseases named in the same sentence as SST in open-access papers (continued):
Sharing a sentence is not in itself a finding about the gene and the disease.
Anxiety (56 papers, 2013 to 2025). Intense feelings of nervousness, tension, or panic often arise in response to interpersonal stresses. "Our findings reveal that 5-HT4Rs are expressed by both PV+ and SST+ GABAergic interneurons and that their pharmacological activation attenuates aberrant neural synchronization associated with memory deficits and anxiety." (PMID 40332153, 2025). "Here we report that the loss of mGlu5 in SST+ neurons decreased anxiety-like behavior and freezing during the retrieval of fear memory involving a reduction in theta frequency oscillatory activity in the mPFC and vHPC." (PMID 38575807, 2024). "Loss of mGlu5 in SST+ neurons elicited excitatory synaptic dysfunction in a region and sex-specific manner together with a range of emotional imbalances including diminished social novelty preference, reduced anxiety-like behavior and decreased freezing during retrieval of fear memories." (PMID 38575807, 2024). "Considering the role of SST expression in the amygdala on avoidance behavior and in modulation of anxiety, we evaluated the effect of LCD exposure on SST expression in the MeA by RNAscope and immunofluorescence at ZT2, ZT8, ZT16, and ZT22." (PMID 38952923, 2024). "In contrast to the pro-resilience effects of SST neurons, we found that increased PV neuron activity has detrimental effects in that it exacerbates anxiety and anhedonia-like behavior in stress-exposed animals." (PMID 39041032, 2024). "Altogether these data suggest sexual dimorphism in the contribution of mGlu5 to the regulation of social and anxiety-like behavior by SST+ neurons." (PMID 38575807, 2024). "The SST gene is an important participant in biological pathways such as stress response, specifically the control of post-stress anxiety relief by activating the reward system with self-grooming." (PMID 39202342, 2024). "Recently, Kelly Tan's lab reported the involvement of SST-positive neurons in the ZI in the regulation of anxiety behavior." (PMID 36260252, 2023). "Intriguingly, the somatostatin (SOM), calretinin (CR), and vesicular glutamate transporter-2 (VgluT2) expressing cells in ZIR encoded and modulated different components of anxiety." (PMID 36837844, 2023). "They found that the SST-positive neurons in the ZI are activated when mice are in anxiety-inducing environment." (PMID 36260252, 2023). "SST neurons in the frontal cortex modulate anxiety-like behavior, and SST knock-out mice display elevated anxiety and corticosterone levels." (PMID 37031222, 2023). "DG PV interneurons modulate anxiety, social interaction, and memory extinction; nevertheless, DG SST interneurons are required for contextual and spatial overlapping memories." (PMID 37545878, 2023). "The analysis of genes and gene mutations associated with anxiety and trauma disorders are still in its infancy, but genes associated with kindling discussed in this paper (CRF and somatostatin) are showing up in these analyses." (PMID 35993088, 2022). "We previously showed that acute pharmacogenetic inhibition of SST+ interneurons increased anxiety-like behavior, and that chronic inhibition (3 weeks) showed an opposite effect, which suggests homeostatic rebalancing occurred." (PMID 35280164, 2022). "In this study, we established a chronic inflammatory pain model and observed that this model induced anxiety-like behaviors and decreased the numbers of parvalbumin (PV) and somatostatin (SOM) positive cells." (PMID 34290586, 2021). "Enhancing excitatory drive on the CeA SST neurons paradoxically disinhibits SST neurons in the oval nucleus in a kappa opioid receptor dependent manner to promote anxiety." (PMID 32536856, 2020). "Intracerebroventricular and intra-amygdala administrations of somatostatin induces anxiolytic and anti-depressant effects in rats while somatostatin KO mice show hyperactivity and anxiety-like behavior." (PMID 25386163, 2014).
Anxiety (continued). "On the other hand, NPY and SST themselves are powerful modulators of anxiety-related behavior and have anxiolytic properties when administered to the amygdala." (PMID 24478650, 2014). "In this study, we identified SST as a mediator of such circadian regulation of anxiety-like behavior in mice and describe the corresponding modulation of SST expression within the basolateral amygdala." (PMID 24376834, 2013). "Mice with intra-amygdalar and intra-septal microinfusions of somatostatin-14 and somatostatin-28 display reduced anxiety-like behavior in the elevated plus-maze and shock-probe tests." (PMID 24058344, 2013). "Others report greater down-regulation of the GABA neuronal marker somatostatin in women with MDD, that somatostatin and GABA-synthesizing enzymes are sensitive to X-chromosome polymorphisms, and that genetic sex modulates both GABA related gene expression and anxiety behaviours." (PMID 37153459, 2023). "Specifically, SST+ and PKCδ+ neurons are mutually inhibiting, and activation of SST neurons leads to inhibition of PKCδ neurons projecting to the CeAM, resulting in a disinhibition of the CeAM outputs to promote anxiety-like behaviors." (PMID 35866156, 2022). "Also, the disinhibition of SST positive interneurons leads to reduced anxiety in the elevated plus maze and despair-like behavior in FST42." (PMID 33580180, 2021). "Therefore, the anxiety-like behavior in Dox-treated Gad1tTA/STOP−tetO mice may be due to GAD67 knockdown from somatostatin-expressing GABA interneurons in cortical and hippocampal areas." (PMID 33413507, 2021). "Evidence suggests that somatostatin (SST) is one neuropeptide with potent anxiolytic properties and a role in fear memory formation, which may thus hold significant potential for the treatment of anxiety- and stress-related disorders." (PMID 24376834, 2013). "Removing PTEN selectively in postnatal somatostatin neurons has been shown to be sufficient for the expression of ASD behaviors such as social deficits, repetitive behaviors, and anxiety." (PMID 40642101, 2025). "Considering the role of somatostatin (SST) in the amygdala in the circadian modulation of anxiety, we assessed Per1 and c-FOS expression in SST neurons in the MeA." (PMID 38952923, 2024). "In agreement with previous work, we found no significant impairments in percentage of time spent in the open arms of the elevated plus maze task, a measure of anxiety, for the Dlx5/6, VIP, PV, or SST mutants compared to controls." (PMID 32343226, 2020). "It was shown that SST INs and SSTR4 play regulatory roles in anxiety and mild stress-induced responses in the amygdala." (PMID 31873798, 2020). "Some studies have also shown that SST and NPY have significant anti-anxiety effects, with a prominent involvement of the amygdalar circuitry." (PMID 32765318, 2020). "Here, we investigated the role of PTEN in somatostatin neurons in amygdala circuits, confirming that KO of PTEN in SOM+ neurons is sufficient to increase anxiety and expanding the behavioral phenotype by demonstrating elevated fear and a heightened acoustic startle response." (PMID 40642101, 2025). "AAV-hM3Dq mediated chronic activation of SST neurons in the prelimbic cortex (PLC) had antidepressant drug-like effects on anxiety- and anhedonia-related motivated behaviors in male but not female mice." (PMID 39041032, 2024). "This is in line with other reports showing that acute chemogenetic inhibition of somatostatin interneurons in the mPFC increased anxiety-like behavior in the EPM test, but not the OFT." (PMID 36808099, 2023).
Anxiety (continued). "Different species of GABACeA neurons, including those expressing adrenocorticotropin-releasing hormone (CRH), protein kinase C delta (PKCδ), somatostatin (SOM), and neurohypophysin, may have different roles in pain and anxiety regulation." (PMID 36710934, 2022). "In addition, CeA neurons can express several neuropeptides that play important roles in fear and anxiety behaviors such as CRF, enkephalins, dynorphins, somatostatin and NPY." (PMID 31167849, 2019). "Further evidence indicates that BDT attenuates anxiety- and depressive-like behaviors in chronic unpredictable stress (CUS) mice via AMPA receptor activation, while its modulation of miRNA-144-3p-mediated GABAergic transmission effectively reverses somatostatin (SST)-positive neuronal deficits." (PMID 41471275, 2025). "Finally, we identified that the majority GABAergic input neurons, which innervate sNAcPV cells, were expressing somatostatin (SOM), and also revealed that coordination between SOM- and PV- cells functioning in the BNST → NAc circuit has an inhibitory influence on anxiety-like responses." (PMID 32555286, 2021). "In addition, we recently reported that mice lacking GAD67 in somatostatin-expressing GABA interneurons demonstrated anxiety-like behavior in the open-field test without affecting locomotor activity." (PMID 33413507, 2021). "Increased SST in the BLA may exert anxiolytic effects via activation of the SST type 2 receptor (SST R2) and could in fact explain both the reduced anxiety-like behavior of SST+/+ mice and the failure of SST-/- mice to show this change during the second half of the active phase." (PMID 24376834, 2013). "In the remainder of the article, we will focus on somatostatin and CRF as examples of kindling mechanisms in the amygdala, hippocampus and prelimbic cortex that may provide clues to how excitatory and inhibitory neuropeptides may regulate transitions from normal fear to pathological anxiety." (PMID 35993088, 2022). "Deletion of Fmr1 in PV+, but not somatostatin-positive (SST+) neurons, resulted in abnormal anxiety and social behaviors, and dysregulated de novo protein synthesis." (PMID 41469555, 2025). "PKCδ-negative neurons are represented by somatostatin- or CRF-positive neurons, and it has been reported that these three cell types cover the majority of CeL neurons and regulate fear and anxiety behaviors." (PMID 35476439, 2022).
Alzheimer disease (39 papers, 2010 to 2026). A progressive, neurodegenerative disease characterized by loss of function and death of nerve cells in several areas of the brain leading to loss of cognitive function such as memory and language. "We further describe the causal relationship between pathophysiological changes in SST function and various neurological disorders, such as Alzheimer's disease." (PMID 33742131, 2021). "It has been reported that memory loss in patients with Alzheimers Disease (AD) may have been derived from deficits in somatostatin function." (PMID 38426092, 2024). "The dysregulation of SST-SSTRs has been implicated in diseases such as Alzheimers diseases." (PMID 38426092, 2024). "Interestingly, VIP and SST are implicated in the pathogenesis of neurodegenerative diseases, including Alzheimer's disease and Parkinson's disease (PD) through reducing the production of inflammatory mediators such as TNF-α and IL-1β." (PMID 32410857, 2020). "Our results reveal that AβO1–42 causes synapse-specific dysfunctions in PV and SST interneurons and that optogenetic modulations of these interneurons present potential therapeutic targets for restoring hippocampal network oscillations and synaptic plasticity impairments in Alzheimer’s disease." (PMID 31937327, 2020). "Four hub genes, GFAP, NPY, SNAP25, and SST, were found as possibly hub aging-related genes in Alzheimer’s disease from machine algorithms by adopting the random forest, LASSO, SVM, and Boruta models." (PMID 41009659, 2025). "GSEA of NPY and SST revealed that Alzheimer’s disease, the cytokine–cytokine receptor interaction, and the notch signaling pathway showed an overall upregulation trend." (PMID 41009659, 2025). "The neuroendocrine peptide somatostatin (SST) has long been thought of as influencing the deposition of the amyloid β peptide (Aβ) in Alzheimer’s disease (AD)." (PMID 36759538, 2023). "Somatostatin (SST), a growth hormone inhibitory peptide, was found to play an important role in many CNS pathological conditions, such as Alzheimer’s disease, Parkinson’s disease, Huntington’s disease, and demyelinating disease." (PMID 34489947, 2021). "As these effects are closely related to cognition, we believethat the results of this study have strengthened the continued evaluationof the somatostatin peptide as a therapeutic option to amelioratethe cognitive dysfunction presented in Alzheimer’s disease." (PMID 34170117, 2021). "Thus, our results suggest that SST interneurons’ neural circuit dysfunction could explain the tLTP impairment caused by acute application of AβO1–42 resembling early stages of Alzheimer’s disease, further supported by our in silico hippocampal network simulation." (PMID 31937327, 2020). "PV interneurons’ spike amplitude, membrane potential, and firing rate are decreased while SST interneurons’ structural plasticity and axonal sprouting are impaired in Alzheimer’s disease mouse models." (PMID 31937327, 2020). "Since we optically stimulated theta oscillations in order to induce gamma oscillations in vitro, our data cannot resolve the individual contribution of PV or SST interneurons on theta oscillation impairment in Alzheimer’s disease." (PMID 31937327, 2020). "It has been reported that SST expression is reduced by 50% in Alzheimer’s disease and that it is related to the formation of Aβ oligomers." (PMID 32140092, 2020). "In Alzheimer’s disease, somatostatin expression is decreased by 50% in the AONca and co-localizes with amyloid β, whereas parvalbumin and somatostatin levels are up- and downregulated, respectively, in the piriform cortex." (PMID 29259548, 2017). "The gene somatostatin (SST), which regulates the endocrine and nervous system function, and its involvement in Alzheimer's disease, and the transcription factor KLF14 involved in metabolism were linked to model markers." (PMID 28808499, 2017).
Alzheimer disease (continued). "Whereas Aβ is best known for its role in Alzheimer disease (AD) as the main constituent of amyloid plaques, SST is intermittently stored in amyloid-form in dense core granules before its regulated release into the synaptic cleft." (PMID 32309597, 2017). "FD reduced the amyloidal burden, attenuated oxidative stress, and assisted in somatostatin activation—the signatures of attenuation of Alzheimer's disease, Parkinson's disease, and affective disorder." (PMID 24632812, 2014). "Decreased CSF somatostatin and decreased somatostatin immune-reactivity across cortical and subcortical regions is reported in subjects with Alzheimer’s disease, including temporal cortex, frontal cortex, and hippocampus." (PMID 24058344, 2013). "The deposition of β-amyloid (Aβ) into senile plaques and the impairment of somatostatin-mediated neurotransmission are key pathological events in the onset of Alzheimer's disease (AD)." (PMID 22509294, 2012). "NEP inactivates a wide range of peptide substrates including enkephalins, neurokinin A, substance P, bradykinin, endothelins, somatostatin, adrenomedullin, bombesin‐like peptides, glucagon, thymopentin as well as the amyloid‐β (Aβ) which accumulates in Alzheimer's disease (AD)." (PMID 35212467, 2022). "We have shown that treatment with SST-scFv8D3generated multiple anti-Alzheimer’s disease effects." (PMID 34170117, 2021). "However, over the last three decades, research on somatostatin in Alzheimer’s disease has been scarce in humans." (PMID 34445147, 2021). "Inthis study, we demonstrate the ability of the SST peptide witha protein-based BBB transporter (SST-scFv8D3) to regulate the levelsof several proteins in the hippocampus of the APPswe transgenic mousemodel of Alzheimer’s disease." (PMID 34170117, 2021). "Although many studies manipulated PV interneurons in Alzheimer’s disease studies, our study is the first to directly show how manipulation of SST interneurons could alleviate Alzheimer’s disease-related dysfunctions." (PMID 31937327, 2020). "Thus, the specific manner in which PV and SST interneurons are affected as the pathologies of Alzheimer’s disease progress with age in vivo to disrupt synaptic plasticity requires further investigation." (PMID 31937327, 2020). "This could signify a previously unrecognized role of somatostatin in the development of Alzheimer’s disease." (PMID 28650319, 2017). "Recently, PRKXP1, SST and TNCRNA (also known as NEAT1, listed second by information gain) were identified by Squillario and Barla as part of a 39 gene signature implicated in Alzheimer’s disease." (PMID 23066814, 2012). "The mechanisms underlying the preferential vulnerability of SST-expressing neurons in Alzheimer’s disease (and, to a minor extent, in Parkinson’s disease) are not known but analysis of the available data could shed light on their etiology." (PMID 32140092, 2020). "Interestingly, both VIP and SST were reported to exert protective effects in neurodegenerative diseases, including Alzheimer's disease and PD through inhibiting the microglial activation and expression of the cytotoxic mediators, such as TNF-α, IL-1β, and prostaglandin E2." (PMID 32410857, 2020). "Although we did not observe altered expression of SST in PBMCs, an age-related decline in expression has previously been reported in the brain, and this decline has been linked to Alzheimer's disease." (PMID 24789080, 2014). "Moreover, genetic deletion of somatostatin leads to reduced hippocampal neprilysin inactivity and increased Aβ42-formation also in young animals, which suggests a potential protective role of somatostatin in the development of Alzheimer’s disease and cognitive deficits." (PMID 30903571, 2019). "For example, modulation of hippocampal theta activity by somatostatin positive, but not parvalbumin positive, GABAergic neurons in a mouse model of Alzheimer’s disease has been demonstrated." (PMID 34966904, 2021).
Alzheimer disease (continued). "Altogether, we can conclude that somatostatin expression is highly reduced in the human hippocampus, but not the olfactory bulb, and may play a role in Alzheimer’s disease pathogenesis." (PMID 34445147, 2021). "Also, parvalbumin-positive (PV) and somatostatin-positive (SST) interneurons, the two major subtypes of hippocampal interneurons that are critically involved in oscillogenesis, are reported to be impaired in mouse models of Alzheimer’s disease." (PMID 31937327, 2020).